RECK (reversion inducing cysteine rich protein with kazal motifs)
Diseases named in the same sentence as RECK in open-access papers (continued):
Sharing a sentence is not in itself a finding about the gene and the disease.
cervical carcinoma (continued). "The expression of SerpinE1/PAI-1 and TIMP2 targets also correlated with RECK mRNA levels in cervical cancer samples." (PMID 34066355, 2021). "We previously showed that RECK expression is down regulated in most cervical cancer derived cell lines and in cervical lesions." (PMID 34066355, 2021). "Cell adhesion regulation was one of most enriched pathways in RECK+ tumors in mice and, also, in cervical cancer patients." (PMID 34066355, 2021). "This approach will be crucial to determine the potential role of RECK as an immunotherapeutic target for the treatment of cervical cancer." (PMID 34066355, 2021). "We first determined the levels of RECK mRNA in a series of cervical cancers or cervical intraepithelial neoplasias (CIN) datasets available in GEO open-access database." (PMID 34066355, 2021). "Here, we showed that RECK over expression reduced the tumorigenic capacity of cervical cancer cells in vivo." (PMID 34066355, 2021). "Two of the somatic mutations COSM1177811 in RECK and COSM1036559 in ATP6V1A were observed in Endometrium." (PMID 31338326, 2019). "We also show that RECK protein expression is down-regulated in high-grade cervical lesions and cervical cancer." (PMID 22438955, 2012). "We have previously shown that RECK mRNA expression is down-regulated in HPV16-positive cervical carcinoma cell lines." (PMID 22438955, 2012). "Consequently, both miR-21 and RECK present themselves as potential targets for gene therapy aimed at curbing cervical cancer growth and metastasis." (PMID 39512697, 2024). "Thus, the expression of miR-21 microRNA is inversely correlated with RECK expression, suggesting that RECK is a miR-21 target gene in HPV16+ human cervical cancer cells." (PMID 38612895, 2024). "Thus, RECK downregulation is a consistent and clinically relevant event in the natural history of cervical cancer." (PMID 38612895, 2024). "To determine whether the RECK gene is a cellular target of miR-21 in cervical cancer cells, we analyzed RECK gene expression in CaSki and SiHa cells transfected with pSIMIR21-5P plasmid, using end-point RT-PCR." (PMID 38612895, 2024). "Our findings are useful to further understand the biology of cervical cancer and can help to determine if RECK may be a good therapeutic target for cervical cancer treatment in the future." (PMID 34066355, 2021). "Similarly, we observed reduced RECK expression in invasive cervical carcinomas (CC), when compared to normal cervical tissue in both GSE7803 and GSE39001 datasets." (PMID 34066355, 2021). "Besides, we show that RECK down regulation is an early trait in cervical cancer history and that RECK levels correlates with protease inhibitors expression, cervical lesions progression, presence of metastases and treatment response in clinical samples." (PMID 34066355, 2021). "Taken together, our results suggest that inhibition of RECK expression by HPV oncogenes may play a role during cervical cancer onset/progression." (PMID 22438955, 2012). "All in all, our results suggest that RECK down-regulation may be important in the natural history of cervical cancer." (PMID 22438955, 2012). "Taken together, our results indicate that inhibition of RECK expression by HPV oncogenes may play a role during cervical cancer onset/progression." (PMID 22438955, 2012). "This study will help to determine if RECK could represent a new biomarker of cervical cancer progression and a potential target for therapy." (PMID 22438955, 2012). "Therefore, we believe that this result further support the notion that RECK inhibition is an important event in cervical cancer biology." (PMID 22438955, 2012). "Therefore, miR-21 and RECK may be potential therapeutic targets in gene therapy for cervical cancer." (PMID 38612895, 2024).
cervical carcinoma (continued). "In the present study, CaSki and SiHa cells (both cervical cancer cells HPV16+) were used to investigate whether siRNA-mediated gene silencing specific to miR-21 expressed in plasmids could alter the expression of the RECK human gene." (PMID 38612895, 2024). "Besides, we analyzed RECK expression in cervical cancer samples." (PMID 34066355, 2021). "Finally, we generated a model for the RECK+ effect on cervical cancer." (PMID 34066355, 2021). "Herein, we describe the effect of siRNAs to miR-21 expressed in plasmids on RECK gene expression and protein expression in HPV-transformed cervical cancer cells." (PMID 38612895, 2024). "Furthermore, RECK could be a promising prognostic biomarker and may shape a low-metastasis microenvironment, while miR-21 may shape high-tumor progression in patients with cervical cancer." (PMID 38612895, 2024). "We found a moderate but significant positive correlation between RECK mRNA and SerpinE1 and TIMP2 mRNA levels in cervical cancer samples." (PMID 34066355, 2021). "RECK expression was determined by immunoblot in HFKs transduced with HPV16 oncoproteins and in three human cervical cancer-derived cell lines (SiHa, CaSki and C33A)." (PMID 22438955, 2012). "It is worth noting that we also detected reduced RECK levels in C33A cells, a HPV-negative cervical cancer cell line." (PMID 22438955, 2012). "Determining that MRE-binding sites from the RECK 3-UTR sequence belong to miR-21, we hypothesize that these MRE recognition sites are involved in the regulation of RECK gene expression in cervical cancer cells." (PMID 38612895, 2024). "The results presented here clearly support the notion that RECK overexpression has a negative effect on the miR-21-mediated tumorigenic potential of HPV-transformed cervical cancer cells." (PMID 38612895, 2024). "The current study has not yet addressed the mechanisms by which RECK expression is reduced along the development of cervical cancer." (PMID 34066355, 2021). "Altogether, we show that increased RECK expression reduced the tumorigenic potential of HPV-transformed cells both in vitro and in vivo, and that RECK down regulation is a consistent and clinically relevant event in the natural history of cervical cancer." (PMID 34066355, 2021). "Finally, we analyzed RECK and MMP-9 expression levels in clinical samples from patients diagnosed with cervical cancer and observed (I) downregulated RECK protein expression and (II) upregulated MMP-9 protein expression in cervical cancer when compared to CIN 1 or normal cervical tissue 27,31." (PMID 30208169, 2018). "In addition, our group has shown that the expression of the MMP inhibitor (MMPI) reversion-inducing protein cysteine-rich protein with kazal motifs (RECK) is downregulated in high-grade CIN and cervical cancer samples when compared with low-grade CIN and control samples." (PMID 30208169, 2018).
non-small cell lung carcinoma (10 papers, 2011 to 2025). A group of at least three distinct histological types of lung cancer, including non-small cell squamous cell carcinoma, adenocarcinoma, and large cell carcinoma. "In non-small cell lung cancer patients, RECK promoter methylation has a higher incidence of lymph node metastasis." (PMID 22428065, 2012). "The suppression of RECK expression has been found in the studies of a number of human tumors including colorectal, breast, pancreas, gastric, hepatocellular, prostate, and non-small cell lung carcinoma." (PMID 21573219, 2011). "Moreover, RECK suppresses cancer stem cells (CSCs) self-renewal and maintenance via mediating the activation of Notch1 signaling regulated by miR-221/22 in non-small cell lung cancer." (PMID 37904179, 2023).
pancreatic cancer (10 papers, 2009 to 2024). "Studies have mentioned the role of RECK in tumors including lung, breast, prostate, oral, digestive tract, liver, and pancreatic cancers." (PMID 33987019, 2021). "Pancreatic cancer patients with higher RECK expression showed statistical better prognosis as compared to that with negative RECK expression." (PMID 27530410, 2016). "For instance, RECK expression in pancreatic cancer tissue was significantly lower than in adjacent normal tissues and was negatively associated with MMP-2 activation and tumor invasive ability." (PMID 19995435, 2009). "In addition, RECK expression is markedly aberrant in many different tumors, including lung, bladder, breast, and pancreatic cancer." (PMID 38686051, 2024). "Moreover, TGF-β1 treatment of Panc-1 cells, a pancreatic cancer cell line, led to a twofold increase in RECK protein levels without any effect on RECK mRNA levels, which was dependent on the activation of the Smad dependent pathway." (PMID 26247610, 2015).
glioblastoma (9 papers, 2012 to 2025). The most malignant astrocytic tumor (WHO grade IV). "On the other hand, RECK over expression has been associated with actin filaments rearrangement and decreased migratory ability and invasive potential in a human glioblastoma multiforme model." (PMID 22438955, 2012). "RECK is regulated by miR-21 and is involved in the invasion and metastasis of glioblastoma, and has also been shown to affect the survival rate of patients with this type of tumor." (PMID 35123404, 2022). "We further investigated the expressional profile of RECK in glioblastoma multiforme (GBM) tumor tissues." (PMID 28208619, 2017). "In CD133+ glioblastoma cells, the expressions of MMPs and RECK were induced by miR-125b, and the authors suggested that the functional inhibition of RECK increases cancer stem cell function." (PMID 24376819, 2013). "Moreover, this alternatively spliced RECK variant appear to have opposing effects compared to canonical RECK (Long RECK) and may serve as prognostic markers in glioblastoma patients." (PMID 34205376, 2021).
colon carcinoma (7 papers, 2009 to 2026). "Results demonstrated that RECK mutants lacking the MRE had augmented tumor/metastasis-suppressor activities and confirmed that miR-21 is involved in the post-transcriptional downregulation of the RECK gene in colon cancer cells." (PMID 38612895, 2024). "Takeuchi and colleagues found RECK downregulated in most colon cancer specimens compared with surrounding normal tissue, and low RECK expression in lymph nodes with a high metastatic rate." (PMID 19995435, 2009). "High expression of miR-221 enhances the invasion and metastasis of colon cancer cells (CRC) by targeting CDKN1C and RECK." (PMID 41602427, 2026). "Thus, attempts were made to restore RECK expression using DNA methyltransferase (DNMT) inhibitor, 5-aza-2′deoxycytidine (5-aza-dC), in colon cancer and salivary adenoid cystic carcinoma." (PMID 29805750, 2018). "Interestingly, a recent report also revealed that miR-15b holds the ability to negatively modulate targeted RECK in the HT1080 human fibrosarcoma cell line and Caco-2, a colon carcinoma cell line." (PMID 27530410, 2016). "MiR-373 is an oncogene and can induce tumor initiation and progression in testicular germ-cell tumors by targeting tumor suppressor LATS2, and invasion and metastasis by targeting CD44, RECK, mTOR and SIRT1 in breast, colon cancer and fibrosarcoma, respectively." (PMID 26258411, 2015).
fibrosarcoma (7 papers, 2009 to 2016). A malignant mesenchymal fibroblastic neoplasm affecting the soft tissue and bone. "We previously observed that forced expression of RECK in fibrosarcoma results in reduced tumor vessel branching, increased vessel diameter, and death of tumor cells distant from expanded blood vessels." (PMID 20691046, 2010). "Vascular sprouting is suppressed in ectopic tumors derived from RECK-expressing fibrosarcoma cells, implicating RECK also in tumor angiogenesis." (PMID 19226458, 2009). "Using Matrigel invasion chamber assay in vitro and in experimental and spontaneous metastasis assays in vivo, the experiments in this study artificially restored RECK expression in tumor cells (such as HT1080 fibrosarcoma or B16 melanoma), in which endogenous RECK was undetectable." (PMID 22428065, 2012).
osteosarcoma (7 papers, 2017 to 2022). A usually aggressive malignant bone-forming mesenchymal neoplasm, predominantly affecting adolescents and young adults. "RECK protein expression is negatively associated with miR-21 expression in human osteosarcoma tissues, indicating that miR-21 potentially controls RECK." (PMID 34671398, 2021). "Our second in vitro model uses a cell line, MG63, derived from human osteosarcoma that expresses abundant RECK and efficiently forms FBN fibers." (PMID 32730638, 2021). "In addition, curcumin deregulated miR-21 and upregulated RECK to inhibit Wnt/β-catenin signaling pathways and lead to inhibition of osteosarcoma cell proliferation." (PMID 34671398, 2021). "In osteosarcoma, it modulates cell invasion and migration by directly targeting RECK and PTEN." (PMID 29113367, 2017).
atherosclerosis (5 papers, 2020 to 2024). A disease characterized by the build-up of fatty material and calcium deposition in the arterial wall resulting in partial or complete occlusion of the arterial lumen. "Although further research is required to fully explore the pathogenic mechanism of RECK splicing in plaque vulnerability, the RECK splice variants in the meantime could nevertheless act as promising biomarkers to monitor atherosclerosis." (PMID 34573314, 2021). "TIMP3 and RECK have also been reported to mediate the inhibitory effects of interleukin-32α (IL-32α) on endothelial inflammation, smooth muscle cell activation, and atherosclerosis development." (PMID 32612540, 2020). "Therefore, TRAF3IP2 and RECK could serve as effective therapeutic targets in atherosclerosis development and progression." (PMID 39451191, 2024). "RECK is a membrane-anchored inhibitor of matrix-degrading metalloproteinases and inflammation, suggesting that its increased expression may have protective effects in atherosclerosis." (PMID 37830075, 2023).
Hyperglycemia (5 papers, 2018 to 2022). An increased concentration of glucose in the blood. "In the mouse model hyperglycemia suppressed the anti-fibrotic factor “reversion inducing cysteine rich protein with Kazal motifs” (RECK) in the kidney, which causes an increase of renal periarterial and interstitial fibrosis." (PMID 30922297, 2019). "Our future studies will determine the molecular mechanisms underlying RECK regulation by hyperglycemia/EMPA." (PMID 30060748, 2018). "Another reported inhibitor of MMPs is the membrane-anchored protein RECK whose expression is increased by hyperglycemia." (PMID 35045102, 2022). "Furthermore, EMPA rescued hyperglycemia-induced suppression of the anti-fibrotic factor, RECK, in the diabetic kidney." (PMID 30060748, 2018). "However, it is not known whether hyperglycemia alone suppresses RECK expression in the kidney." (PMID 30060748, 2018).
melanoma (5 papers, 2012 to 2025). A malignant, usually aggressive tumor composed of atypical, neoplastic melanocytes. "MiR-182 regulated RECK expression and inhibited the proliferation of malignant melanoma cells, thereby providing a novel target for molecular therapy in the treatment of malignant melanoma." (PMID 40861221, 2025). "In human malignant melanoma tissues, the reversion-inducing cysteine-rich protein with Kazal motifs (RECK) was downregulated." (PMID 40861221, 2025). "Sets of primers were designed to amplify the sequences corresponding to the RECK alternative transcripts using total RNA from melanoma 1205 Lu cells." (PMID 26431549, 2015). "Other newly identified targets of miR‐21, including Maspin, MARCKS, and RECK, have been shown to participate in decreasing cancer cell invasion through matrigel and therefore warrant exploration into their ability to do so in melanoma." (PMID 25587717, 2015). "MiR-182 regulated RECK expression and inhibited the proliferation of malignant melanoma cells." (PMID 40861221, 2025). "In addition to miR-214/CADM1 and miR-182/RECK, recent studies have demonstrated that the exosomal miR-29c-3p derived from M1 macrophages inhibits the invasiveness of melanoma cells through ectonucleotide pyrophosphatase/phosphodiesterase 2 (ENPP2)." (PMID 40861221, 2025). "Moreover, low levels of miR-182 promoted RECK expression in malignant melanoma cells." (PMID 40861221, 2025). "Additionally, the canonical RECK expression levels positively correlated with TIMP-3 expression, as we have previously reported in a melanoma progression model, and RECK, RECK-B and RECK-I expressions levels correlated positively with TIMP-2." (PMID 26431549, 2015).
breast tumor (4 papers, 2009 to 2021). "Low RECK expression was previously correlated with increased capacity of vessel formation, invasion and onset of local and distant metastases in animal models of breast tumor." (PMID 34066355, 2021).
cervical (3 papers, 2012 to 2024). "Our understanding of the RECK molecular regulation mechanism mediating miR-21 microRNA function in cancer generally and the cervical carcinogenesis process specifically remains limited." (PMID 38612895, 2024). "We previously reported the existence of an inverse correlation between RECK expression and cervical disease progression." (PMID 34066355, 2021). "In cervicitis tissue, strong RECK signal was observed in the membrane and cytoplasm of most cells in all cervical epithelium layers." (PMID 22438955, 2012). "We next analyzed RECK gene expression according to cervical disease outcomes." (PMID 34066355, 2021). "RECK expression in cervicitis, CIN I, CIN II/III and invasive cervical carcinomas." (PMID 22438955, 2012). "Characterization of RECK in human cervical specimens showed that its expression was higher in cervicitis samples than in CINII/III and invasive carcinoma samples indicating that RECK down-regulation may correlate with lesion grade." (PMID 22438955, 2012).
ischemic stroke (3 papers, 2018 to 2023). A stroke disorder caused by obstruction of blood flow to the brain, due to thrombotic (local blood clot formation) or embolic (due to a blood clot or other material traveling from another site) event. "Therefore, it is necessary to confirm whether miR-21-5p plays a pro-angiogenic role in ischemic stroke by targeting RECK in the future." (PMID 35883438, 2022). "Therefore, the expression and activation of MT1‐MMP promotes angiogenesis in the early ischemic stroke; However, the results also showed that the expression and change trend of RECK was contrary to MT1‐MMP, which means RECK may be a potential inhibitor of MT1‐MMP after stroke." (PMID 30035384, 2018).
liver cancer (3 papers, 2020 to 2021). An epithelial or non-epithelial malignant neoplasm that arises from the liver. "outlining specific SNPs in RECK that are relevant to liver cancer in humans." (PMID 34745017, 2021). "However, the mRNA expression of RECK in liver cancer cell lines (shown in red frame) was higher than most of other digestive cancer cell lines." (PMID 34093791, 2021).
lung adenocarcinoma (3 papers, 2013 to 2016). A carcinoma that arises from the lung and is characterized by the presence of malignant glandular epithelial cells. "In general, downregulation of ZEB1, RECK, TGFBR2 and BMPR2, as well as upregulation of CDK4, CCNE2, EZH2 and DNMT1 has been shown in lung adenocarcinoma and/or squamous cell carcinoma." (PMID 27588394, 2016).